DUXAP10 (double homeobox A pseudogene 10 )
Diseases named in the same sentence as DUXAP10 in open-access papers (continued):
Sharing a sentence is not in itself a finding about the gene and the disease.
tumor (continued). "In the present study, we investigated that pseudogene-expressed lncRNA DUXAP10 was aberrantly expressed in CRC and positively associated with tumor size, pathological stage and lymphatic metastasis." (PMID 28779166, 2017). "Furthermore, the silencing of DUXAP10 demonstrated inhibitory effects on tumor growth in in vivo experiments." (PMID 40556338, 2025). "We also demonstrated that DUXAP10 promoted the formation and growth of OS by tumor formation assay." (PMID 36053455, 2022). "Thus, the molecular mechanisms of DUXAP10 involved in tumor progression should be further explored, contributing to new hopes in tumor treatment." (PMID 35186937, 2022). "Additionally, in vivo xenograft tumor model experiments validated the tumor-promoting role of DUXAP10 in accelerating tumor growth and increasing tumor volumes." (PMID 35186937, 2022). "A high expression level of DUXAP10 was remarkably connected with tumor size and the FIGO stage." (PMID 35186937, 2022). "Collectively, DUXAP10 is highly involved in the tumor cell growth of HCC." (PMID 30996112, 2019). "In addition, we found that the level of lncRNA DUXAP10 was higher in HCC tissues than in adjacent non‐tumour samples and was conversely related to the miR‐1914 expression level in HCC tissues." (PMID 31576658, 2019). "The results showed that DUXAP10 is dramatically elevated in HCC tumor tissues and cell lines." (PMID 30996112, 2019). "In this study, we also found that KLF2 can function as tumor suppressor and its’ expression could be suppressed by DUXAP10 through recruiting PRC2 and LSD1 to its promoter region in GC cells." (PMID 29374493, 2018). "Our results indicated that knockdown of DUXAP10 expression could suppress GC cells tumor growth in vivo." (PMID 29374493, 2018). "Furthermore, tumor stage in DUXAP10 high expression group was higher, and the tumor volume was larger." (PMID 29921308, 2018). "The in vivo investigation also showed that knockdown of DUXAP10 impaired tumor growth." (PMID 28029651, 2017). "The tumor weight of sh-DUXAP10 group was also significantly lower than that in the control group." (PMID 28029651, 2017). "Since the cell cycle of tumor cells is in a rapidly dividing state, to examine whether DUXAP10 affects the proliferation of OS cells by regulating cell cycle, we used flow cytometry assay to detect cell cycle changes in DUXAP10 knockdown U2OS and SAOS2 cells." (PMID 36053455, 2022). "Here, we reported that DUXAP10 could not only repress tumor suppressors LATS1 and KLF2 transcription through epigenetic modification by interacting with PRC2 and LSD1, also can regulate β-catenin mRNA stability by recruiting RNA binding protein HuR at post-transcriptional level in GC cells." (PMID 29374493, 2018). "DUXAP10 knockdown inhibits CRC cell proliferation, induces apoptosis, and increases G0/G1 arrest, suppressing tumor growth in vivo." (PMID 40556338, 2025). "Current studies have revealed that DUXAP10 mainly affects the processes of tumor cell EMT, thus enhancing tumor cell migratory properties in several cancers." (PMID 35186937, 2022). "According to the intersection of up-regulated lncRNAs in GSE18842 and GSE19188, seven lncRNAs (LINC00511, LINC01133, DUXAP10, LINC01296, BBOX1-AS1, AFAP1-AS1 and LINC01116) were found to be highly expressed in NSCLC tumor tissues in both datasets." (PMID 33931086, 2021). "However, the mechanisms of DUXAP10 on the tumor growth in HCC patients remain unclear." (PMID 30996112, 2019). "First, we used the GEO database to show that DUXAP10 was obviously higher in HCC samples than in normal liver tissues, and we confirmed that DUXAP10 was higher in HCC tissues than in neighbouring non‐tumour tissues (P < .05)." (PMID 31576658, 2019). "Knockdown of DUXAP10 exerted tumor-suppressive functions through reducing cell proliferation, migration as well as inducing apoptosis in NSCLC, while DUXAP10 overexpression promoted cell proliferation, and migration." (PMID 28029651, 2017).
tumor (continued). "In this study, we observed that DUXAP10 was up-regulated in CRC tissues which was positively correlated with advanced pathological stages, larger tumor sizes and lymph node metastasis." (PMID 28779166, 2017). "A mechanistic exploration indicated that DUXAP10, by interacting with LSD, facilitated CRC cell growth and suppressed cell apoptosis by downregulating the expression of p21 and PTEN, both recognized tumor suppressors." (PMID 40556338, 2025).
cancer (8 papers, 2017 to 2025). A tumor composed of atypical neoplastic, often pleomorphic cells that invade other tissues. "These associations revealed the potential for DUXAP10 to be used as a prognostic biomarker to predict cancer prognosis and provide guiding recommendations for the future treatment of tumors." (PMID 35186937, 2022). "DUXAP10 is upregulated in various types of cancer and its expression is positively associated with cancer progression and/or metastasis." (PMID 30071685, 2018). "The pseudogene DUXAP10 is located on human chromosome 14q11.2 with a total length of 2398 bp, which is significantly upregulated in human cancers and might be a risk factor for poor prognosis." (PMID 36471952, 2022). "DUXAP10 expression was transcriptionally repressed with CRISPR-interference (CRISPRi), and data supports an extensive role of DUXAP10 in several cancer-promoting phenotypes in ATC, both in vitro and in vivo." (PMID 41375055, 2025). "Previous studies have also shown the significant impact that targeting RNA polymerase II as a therapeutic option in some cancers— further supporting our finding that DUXAP10 expression alters this output." (PMID 41375055, 2025). "We next discuss the DUXAP10 expression level, relevant clinical characteristics, and biological functions in different cancer types." (PMID 35186937, 2022). "In AGS, BGC823, SGC7901, and MGC803 cell lines, DUXAP10 was found to exert cancer-promoting functions through the activation of cell proliferation, cell cycle progression, invasion, and migration." (PMID 35186937, 2022). "In this review, we summarize the roles of DUXAP10 in different cancers, including dysregulated expression, related clinical characteristics, biological functions underlying molecular mechanisms, and potential clinical applications." (PMID 35186937, 2022). "Multiple studies have found that DUXAP10 widely regulates vital biological functions related to the development and progression of cancers, including cell proliferation, apoptosis, invasion, migration, and stemness, through different molecular mechanisms." (PMID 35186937, 2022). "Recently, the pseudogene DUXAP10 was shown to be overexpressed in various human cancers and emerged as a key cancer regulator." (PMID 36471952, 2022). "The novel lncRNA DUXAP10 was newly reported to be abnormally overexpressed in several cancers and positively correlated with poor clinical characteristics of cancer patients." (PMID 35186937, 2022). "The aim of this review was to recapitulate current findings regarding the roles of DUXAP10 in cancers and evaluate the potential of DUXAP10 as a novel biomarker for cancer diagnosis, treatment, and prognostic assessment." (PMID 35186937, 2022). "Migration and metastasis of cancer cells is an important factor in the progress of cancer, we conducted a transwell test of DUXAP10 on NSCLC cell migration and invasion." (PMID 28029651, 2017). "Additionally, DUXAP10 contributed to cancer progression through its involvement in several cellular functions in T24 and 5,637 cells, including cell cycle progression, proliferation, and apoptosis." (PMID 35186937, 2022). "Interestingly, an emerging role of DUXAP10 in promoting the transition of CSCs has been observed, which is essential for the tumorigenicity of cancer cells." (PMID 35186937, 2022). "However, the detection of DUXAP10 in tissue is an invasive and complicated method, and further studies are needed to search for possible noninvasive methods for the diagnosis of cancers using DUXAP10." (PMID 35186937, 2022). "DUXAP10 expression and clinicopathological features in cancers." (PMID 35186937, 2022). "Therefore, a further in-depth understanding of the pro-oncogenic mechanisms of DUXAP10 for cancer treatment is needed." (PMID 35186937, 2022). "As a newfound oncogene, DUXAP10 has been reported to be widely involved in the mediation of several crucial biological processes, such as cell proliferation, apoptosis, and metastasis, in diverse cancer types." (PMID 35186937, 2022).
cancer (continued). "Therefore, DUXAP10 in combination with relevant clinicopathological features can function as an independent prognostic indicator in diverse cancer types." (PMID 35186937, 2022). "Epithelial-Mesenchymal Transition has been found to play important roles in cancer cells invasion and metastasis, and we investigated whether DUXAP10 could affect this process in GC cells by analyzing EMT markers levels after knockdown of DUXAP10." (PMID 29374493, 2018). "Aberrantly expressed DUXAP10 was recently revealed to be involved in a wide range of biological functions and pathological characteristics, and its vital clinical applications in several cancer types are valuable for clinical diagnosis, prognosis, and treatment management." (PMID 35186937, 2022). "Double Homeobox A Pseudogene 10 (DUXAP10) was the top statistically significant differentially expressed gene in ATC compared to normal thyroid tissue (GSE33630) and has been previously established as an overexpressed oncogene in various carcinomas." (PMID 41375055, 2025). "The biological function and expression pattern of DUXAP10 in cancers is not reported until now, and we found that DUXAP10 was significantly up-regulated in NSCLC tissues and cells." (PMID 28029651, 2017). "The oncogenic activity of DUXAP10 may serve as a novel biomarker and therapeutic target for CRC in future cancer clinic." (PMID 28779166, 2017). "Therefore, it can be proposed that the DUXAP10 regulates cell migration and invasion in the broader manner; not in a cancer type specific manner." (PMID 30996112, 2019).
DUXAP10 also shares sentences with these, for which no sentence is quoted: esophageal squamous cell carcinoma (3 papers); esophageal cancer (2); renal cell carcinoma (2); papillary thyroid carcinoma (1); prostate carcinoma (1); uterine corpus endometrial carcinoma (1).